PEMT (phosphatidylethanolamine N-methyltransferase)
Description:
Catalyzes the three sequential steps of the methylation pathway for the biosynthesis of phosphatidylcholine, a critical and essential component for membrane structure. Uses S-adenosylmethionine (S-adenosyl-L-methionine, SAM or AdoMet) as the methyl group donor for the methylation of phosphatidylethanolamine (1,2-diacyl-sn-glycero-3-phosphoethanolamine, PE) to phosphatidylmonomethylethanolamine (1,2-diacyl-sn-glycero-3-phospho-N-methylethanolamine, PMME), PMME to phosphatidyldimethylethanolamine (1,2-diacyl-sn-glycero-3-phospho-N,N-dimethylethanolamine, PDME), and PDME to phosphatidylcholine (1,2-diacyl-sn-glycero-3-phosphocholine, PC), producing S-adenosyl-L-homocysteine in each step. Responsible for approximately 30% of hepatic PC with the CDP-choline pathway accounting for the other 70% (Probable). [Isoform 1]: Catalyzes the three sequential steps of the methylation of 1,2-diacyl-sn-glycero-3-phospho-N-methylethanolamine (PMME) to 1,2-diacyl-sn-glycero-3-phospho-N,N-dimethylethanolamine (PDME) more efficiently than isoform 2. Induces increase in PC species with longer polyunsaturated chains than isoform 2. [Isoform 2]: Produces a higher increase in the level of PC species containing long chains with three double bonds than isoform 1.
Synonyms: PEAMT; PLMT; PEMPT; PEMT2
Tractability: Antibody: UniProt predicts a signal peptide or a membrane-spanning region.
Gene: Protein-coding gene on chromosome 17 (17,505,561 to 17,591,718, reverse strand). Ensembl gene ENSG00000133027.
Subcellular location: Endoplasmic reticulum; Endoplasmic reticulum membrane (Isoform 1); Mitochondrion membrane; Endoplasmic reticulum membrane (Isoform 2)
Subcellular location (Human Protein Atlas): Endoplasmic reticulum; Mitochondria; Cytosol; Vesicles
Pathways (Reactome):
Metabolism: Synthesis of PC
Gene Ontology:
Molecular function: phosphatidylethanolamine N-methyltransferase activity; phosphatidyl-N-methylethanolamine N-methyltransferase activity; S-adenosylmethionine-dependent methyltransferase activity
Biological process: phosphatidylcholine biosynthetic process; positive regulation of cold-induced thermogenesis
Cellular component: endoplasmic reticulum; endoplasmic reticulum membrane; mitochondrial membrane
Genetic constraint (gnomAD): Loss-of-function variants: 18 observed, 20.37 expected, observed/expected ratio (o/e) 0.88, 90% interval 0.61 to 1.31. The upper end of that interval is the gene's LOEUF score, 1.31, which puts it in group 5 of 6, group 1 being the genes least tolerant of losing a copy. Missense variants: 272 observed, 269.04 expected, observed/expected ratio (o/e) 1.01, 90% interval 0.92 to 1.12. Synonymous variants: 123 observed, 119.2 expected, observed/expected ratio (o/e) 1.03, 90% interval 0.89 to 1.2.
Homologues: Orthologues: chimpanzee PEMT (98% identical), macaque PEMT (95% identical), dog PEMT (80% identical), rat Pemt (77% identical), mouse Pemt (68% identical), rabbit PEMT (63% identical), guinea pig PEMT (62% identical), zebrafish pemt (50% identical), tropical clawed frog pemt (47% identical).
Diseases named in the same sentence as PEMT in open-access papers:
PEMT is named in the same sentence as 79 diseases in open-access papers, as found by Europe PMC text mining. Sharing a sentence is not in itself a finding about the gene and the disease. The quoted sentences say what the papers report.
Obesity (27 papers, 2013 to 2025). Accumulation of substantial excess body fat. "Studies on polymorphisms have revealed that the SNP rs4646404 and SNP rs4646343 in the PEMT gene are linked to an increased risk of obesity." (PMID 39409074, 2024). "The observed effect of the PEMT GG genotype on the association between choline intake and HS was independent of the degrees of HS-related metabolic markers, such as obesity, insulin resistance, and dyslipidemia, and the intake of other MDNs in both sexes." (PMID 37513629, 2023). "Our findings support the role of PEMT in FD as well as its association with obesity and diabetes, as demonstrated by a fat depot-specific PEMT mRNA expression in three distinct tissues." (PMID 38069170, 2023). "In the present study, we elucidated the role of the PEMT gene, including the waist–hip-ratio-associated single nucleotide polymorphism rs4646404, and its influence on obesity-related metabolic traits." (PMID 38069170, 2023). "Lower hepatic PEMT expression was also associated with lower BMI, in keeping with the demonstration that PEMT−/− mice are protected from high fat diet-induced obesity and insulin resistance." (PMID 35331317, 2022). "PEMT-deficient mice are protected from HFD-induced obesity and insulin resistance, but develop severe NAFLD." (PMID 28159867, 2017). "In PEMT-knockdown mice, PEMT deficiency was demonstrated to result in a significant reduction in the hepatic ratio of phosphatidylcholine to phosphatidylethanolamine in the case of obesity or overnutrition, which increases the risk of NAFLD." (PMID 37513629, 2023). "On the other hand, decreased PEMT activity caused liver dysfunction in ob/ob mice, and significant alterations to the hepatic phosphatidylcholine: phosphotidylethanolamine molar ratio during obesity or overnutrition appear to promote NASH progression." (PMID 36012560, 2022). "PEMT deficiency leads to various biological changes, including increased hepatic steatosis, attenuated ER stress in diabetic nephropathy, a resistance to diet-induced obesity, and protection against insulin resistance in mice." (PMID 36139111, 2022). "To determine whether a significant relationship between PEMT genotypes and NAFLD risk might be masked by the presence of obesity in our cohort, we also tested the association between PEMT variants and NAFLD in normal weight Caucasian individuals from the UKB." (PMID 36012560, 2022). "PEMT deficiency has been found to result in decreased lipogenesis, which may explain the resistance to high fat diet-induced obesity." (PMID 36139111, 2022). "Compared to wild-type mice, PEMT-deficient mice (Pemt -/-) are resistant to diet-induced hypertrophy of adipocytes in white adipose tissue and are also protected against high fat diet-induced obesity and insulin resistance." (PMID 23724137, 2013). "Intronic cis-regulatory polymorphisms may increase the genetic risk of obesity by modulating PEMT expression." (PMID 23724137, 2013). "Thus, our study suggests an important role for cis-regulatory SNPs in modulating PEMT expression, which in turn may increase genetic susceptibility to obesity by altering phospholipid composition and inducing ER stress in adipocytes." (PMID 23724137, 2013). "PEMT plays a role in several significant diseases, including obesity, obesity-related insulin resistance, HCV infection, type II diabetes, and atherosclerosis." (PMID 39409074, 2024). "PEMT plays a significant role in type II diabetes, as substantiated by the correlation observed between the SNP rs4646404 in the PEMT gene and insulin resistance in individuals with obesity." (PMID 39409074, 2024). "Investigations involving mice with a defective PEMT gene have affirmed the indispensable role of this enzyme in obesity development." (PMID 39409074, 2024). "Here, we reviewed the structural and functional properties of PEMT, highlighting its role in the pathogenesis of obesity, liver diseases, cardiovascular diseases, and other conditions." (PMID 37191416, 2023).
Obesity (continued). "Transcriptional upregulation of PEMT in human AT showed a correlation with WHR adjusted for BMI, indicating its association with an increased genetic risk for obesity." (PMID 38069170, 2023). "In the present study, growth-related genes, GAL, CENPF, and GPC2, obesity-related gene, PEMT, and CYP3A4, P450, TMEM200B genes were found to be associated with BWF." (PMID 35795788, 2022). "This study examined, for the first time, the association between PEMT and MTHFR polymorphisms and fatty acid concentrations in RBC membranes in children with obesity." (PMID 31671528, 2019). "It remains unknown whether the current AI values are sufficient for individuals with obesity, who may have altered hepatic metabolism, reduced PEMT activity, or impaired choline absorption." (PMID 41305668, 2025). "Furthermore, the expression of PEMT in adipose tissue demonstrates a positive correlation with insulin resistance in those with obesity." (PMID 39409074, 2024). "However, knockout of PEMT protects against diet-induced atherosclerosis, diet-induced obesity, and insulin resistance." (PMID 37191416, 2023). "However, the complex role of PEMT in obesity and its related diseases remains incompletely understood." (PMID 38069170, 2023). "Under obesity-induced excess fat accumulation, the increased requirement for PC synthesis may rely on hepatic salvage PC synthesis by the PEMT pathway using folate and betaine-mediated S-adenosylmethionine-derived methyl groups." (PMID 35057441, 2022). "In conclusion, de novo synthesis of choline through PEMT plays an important role in regulating systemic energy metabolism, and the PEMT gene may be a pharmacological target for the treatment of obesity and insulin resistance." (PMID 35795788, 2022). "PEMT−/− mice are also protected from high-fat-diet-induced obesity and insulin resistance." (PMID 36012560, 2022). "The data presented indicate that PEMT inhibitors may be agents for treating or preventing obesity." (PMID 39409074, 2024). "Although the RBC PUFA levels in the present study were not influenced by estimated intakes, they associated significantly with two SNPs in the PEMT and MTHFR genes, suggesting that, in children with obesity, genetic variability could be predictive for PUFA composition in RBCs." (PMID 31671528, 2019). "In addition, pharmacological PEMT inhibition may be beneficial in the treatment of obesity and type 2 diabetes with concomitant diet therapy with fat restriction or use of lipase inhibitors." (PMID 26883167, 2016). "Specific PEMT inhibitors have not yet been developed, but if they are in the future, they hold significant therapeutic potential, particularly for treating obesity." (PMID 39409074, 2024). "The consequences of reduced PEMT expression and activity, such as the absence of obesity in animals fed a high-fat diet, underscore the pivotal role of PEMT." (PMID 39409074, 2024). "Moreover, in a lean mouse model of severe nonalcoholic fatty liver disease, phosphatidylethanolamine N-methyltransferase mice, we observed a 4-fold increase in circulating DPP4, in contrast with previous findings connecting DPP4 release and obesity." (PMID 36472923, 2023). "In mice, lack of phosphatidylethanolamine N-methyltransferase (PEMT) prevents high-fat diet (HFD)-induced obesity and insulin resistance by promoting energy expenditure." (PMID 35232994, 2022). "A previous study reported that mice lacking PEMT were protected against HFD-induced obesity and insulin resistance, confirming the relationship between the down-regulation of PEMT and anti-obesity effects." (PMID 28106735, 2017). "Mice lacking phosphatidylethanolamine N-methyltransferase (PEMT) are protected from high-fat diet (HFD)-induced obesity and insulin resistance." (PMID 28159867, 2017). "When Pemt+/+ mice were fed a HFD for 6 weeks, they developed obesity and insulin resistance, which did not occur in mice lacking PEMT." (PMID 28159867, 2017).
Obesity (continued). "Therefore, an obesity-induced decrease in PCYT2 expression and an increase in PEMT expression may result in decreased PE synthesis, and increased transformation may be the cause of this decreased expression." (PMID 38640132, 2024). "Mice lacking PEMT were already protected against diet-induced obesity and glucose intolerance, and fenofibrate did not have an additive effect on these parameters, nor did it change mRNA levels of genes involved in glucose metabolism in liver or brown adipose tissue in Pemt−/− mice." (PMID 28159867, 2017). "A recent study demonstrates the absence of phosphatidylethanolamine N-methyltransferase (PEMT) promotes an increase in metabolic rate and protects from diet-induced obesity, potentially due to decreasing SERCA efficiency in skeletal muscle." (PMID 34795598, 2021). "In recent years, we have demonstrated that hepatic PEMT plays a role in several aspects of the metabolic syndrome: when mice lacking PEMT were fed a high-fat diet (HFD), they were strikingly protected from obesity and insulin resistance." (PMID 28159867, 2017).
Hepatic steatosis (19 papers, 2010 to 2025). Steatosis is a term used to denote lipid accumulation within hepatocytes. "Reduced expression of PEMT can result in diminished endogenous PC production in chickens, potentially predisposing them to hepatic steatosis." (PMID 40075981, 2025). "Endogenous PC is synthesized from PE by the PEMT gene, which was downregulated in hepatic steatosis groups and shared the same regulatory genomic variants with hepatic steatosis classification in our GWA analysis." (PMID 38837944, 2024). "Vitamin E prevented the progression of hepatic steatosis in phosphatidylethanolamine N-methyltransferase-deficient and high-fat diet mouse models, and the potential mechanisms included suppression of ER stress and hepatic ROS production." (PMID 38296998, 2024). "In humans, PEMT rs7946 polymorphism exerts sex-specific effects on choline requirement and hepatic steatosis (HS) risk." (PMID 37513629, 2023). "Our findings reveal that the effect of daily dietary choline intake on the risk of fatty liver disease is modified by PEMT rs7946 polymorphism and sex." (PMID 37513629, 2023). "It is clear that choline is required for normal liver function, as choline-deficient diets or diminished PEMT activity results in hepatic steatosis." (PMID 36012560, 2022). "Both choline deficiency and low hepatic phosphatidylethanolamine N-methyltransferase (PEMT) activity are associated with hepatic lipidosis (HL) in humans, mice and rats." (PMID 26552767, 2015). "Notably, studies using PEMT-knockout mice have shown that choline deficiency can lead to the development of hepatic steatosis and liver injury, even when a diet supplemented with choline surpasses the required intake amount." (PMID 37513629, 2023). "However, it has been reported that human and rodent female have a lower risk for hepatic steatosis than male, because of higher expression of hepatic PEMT in females." (PMID 35102146, 2022). "In addition, the data of PEMT expression and activity is still limited in viral and autoimmune hepatitis and other diseases such as lipodystrophic patients associated with severe fatty liver and loss of adipose tissues." (PMID 26883167, 2016). "We further identified gene PEMT and duodenal genus Lactobacillus involved in the methionine cycle as crucial contributors to hepatic steatosis, which would be beneficial to study NAFLD in farm animal or humans by providing innovative ideas and methods." (PMID 38837944, 2024). "Altogether our results suggest that a greater induction of PEMT in patients with genotype 3 infection promotes more hepatic steatosis, through the downstream effects on MTP, SREBP 1-c, DGAT1 and other key lipid genes." (PMID 37240132, 2023). "PEMT−/− knockout mice fed a diet high in fat and sucrose rapidly develop hepatic steatosis, inflammation, and fibrosis, which is reversed by dietary choline supplementation." (PMID 36012560, 2022). "The deletion of the PEMT or MAT1 genes results in the development of fatty liver disease in animals." (PMID 26999104, 2016). "This is consistent with previously identified hepatic steatosis in the PEMT KO mice." (PMID 36139111, 2022). "SAH accumulation inhibits PEMT, and SAH-mediated impairment of PEMT is linked to hepatic steatosis." (PMID 35563604, 2022). "In this context, it is interesting to note that the degree of hepatopathy in the MKO mouse model is very similar to that observed previously in the PEMT knockout mouse that incurs hepatic steatosis, which, when exacerbated by reduced dietary choline, results in severe liver injury and death." (PMID 20638879, 2010). "Finally, we found that PEMT could mediate the HCV genotype-specific induction of hepatic steatosis, as PEMT expression was higher in the livers of patients with genotype 3 infection than genotype 1." (PMID 37240132, 2023).
Hepatic steatosis (continued). "We identified 98 and 119 genes that were significantly positively and negatively correlated with hepatic steatosis, respectively, after FDR correction (Padj < 0.05, FDR correction), including trans-eGenes PEMT and TOM1L2." (PMID 38837944, 2024). "Increasing hepatic fatty acid oxidation can compensate for the lower VLDL-triacylglycerol secretion rate and prevent/reverse fatty liver disease in mice lacking PEMT." (PMID 28159867, 2017). "Interestingly, PEMT expression was over 50% higher in liver biopsies from people infected with the HCV genotype 3 than 1, and three times higher than in people with chronic hepatitis B, suggesting that this may account for genotype-dependent differences in the prevalence of hepatic steatosis." (PMID 37240132, 2023). "Low choline diet led to transcriptional changes in peripheral lymphocytes.Gene signature associated with the presence or absence of organ dysfunction (fatty liver and elevated plasma CRP).SNPs in MTHFD1, CHDH and PEMT influence the diet-induced changes in gene expression profile." (PMID 40821837, 2025).
Insulin resistance (17 papers, 2015 to 2025). Increased resistance towards insulin, that is, diminished effectiveness of insulin in reducing blood glucose levels. "Reduced PEMT activity in the liver shields against insulin resistance, linked to a decrease in the PC:PE ratio." (PMID 39409074, 2024). "Although inhibition of PEMT ameliorated insulin resistance in HFD-fed mouse models, it also resulted in MAFLD development due to lower secretion of VLDL." (PMID 35957983, 2022). "Decreased PEMT expression in omental adipose tissue was correlated with lipid deposition and insulin resistance in obese women." (PMID 32399287, 2020). "Mechanistically, animal studies have shown that choline may promote insulin resistance and hyperglycemia in the liver of mice with impaired phosphatidylethanolamine N-methyltransferase function." (PMID 40077680, 2025). "And experimental studies at the animal-level have found several clues linking phospholipid metabolism to insulin resistance through the knockout of phospholipid synthesis enzymes, like phosphatidylethanolamine N-methyltransferase (PEMT) and lysophosphatidylcholine acyltransferase 3 (LPCAT3)." (PMID 38674894, 2024). "PEMT knockout mice exhibited elevated oxygen consumption rates, reduced hepatic gluconeogenesis, and suppressed HFD-induced obesity and insulin resistance." (PMID 35957983, 2022). "Thus, the direct or indirect action of pitavastatin on the phosphatidylethanolamine N-methyltransferase pathway may contribute to its overall effect on the plasma lipidome in prediabetes and insulin resistance, with potential for either a neutral or attenuating effect on risk of development of T2D." (PMID 26486974, 2015). "Mice lacking PEMT, a MAM-localized PC synthesizing protein, were protected against HFD-induced obesity and insulin resistance." (PMID 33329397, 2020). "However, as PEMT is a functional and not a tethering protein, it may not have been the damaged MAM structure that promoted insulin resistance in this study, but rather the impaired MAM function." (PMID 33329397, 2020).